HOTAIR (HOX transcript antisense RNA)
Diseases named in the same sentence as HOTAIR in open-access papers (continued):
Sharing a sentence is not in itself a finding about the gene and the disease.
endometriosis (6 papers, 2021 to 2025). The growth of functional endometrial tissue in anatomic sites outside the uterine body. "Since HOTAIR has been considered as an onco-lncRNA, we next asked the possibility of using HOTAIR as a potential target for treating endometriosis and the associated malignancies." (PMID 33667269, 2021). "Based on our data, we discovered that genetic variations in the exon region (rs1838169 and rs17720428) can potentially stabilize HOTAIR structure (ΔΔG = -6.5 kcal/mol) and showed an increased risk for endometriosis development." (PMID 33667269, 2021). "In this study, we discovered that genetic variations in HOTAIR, especially the SNPs at rs1838169-G and rs17720428-G alleles, can change local RNA structures and define the susceptibility to endometriosis." (PMID 33667269, 2021). "The most responsive downstream targets, genes at the HOXA and HOXD loci, that associated with elevated HOTAIR in severe endometriosis were HOXD10 and HOXA5." (PMID 33667269, 2021). "Our study identified two major downstream targets, HOXD10 and HOXA5, regulated by HOTAIR in advanced endometriosis and the associated ovarian clear cancer cells." (PMID 33667269, 2021). "Findings from our study reveal a genetic linkage of HOTAIR polymorphisms to the susceptibility and pathogenesis of endometriosis." (PMID 33667269, 2021). "To further explore the underlying mechanism of LncRNA HOTAIR in endometriosis, we used TargetScan to predict whether miR-519b-3p might be the target gene of LncRNA HOTAIR." (PMID 36338672, 2022). "We demonstrated in this study that genetic alterations in HOTAIR may be one of the risk factors leading to endometriosis development." (PMID 33667269, 2021). "LncRNA HOTAIR is involved in the development of endometriosis by promoting endometrial stromal cell invasion and migration by increasing PRRG4 expression through sponging of miR-519b-3p." (PMID 40457415, 2025). "Downstream screening using data from clinical and cell-based studies revealed HOXD10 and HOXA5 to be the key regulators for HOTAIR to promote endometriosis progression." (PMID 33667269, 2021). "Our data therefore confirmed potent roles of HOTAIR functional SNPs in endometriosis development, especially for the genetic combination between allelic variations at rs1838169 and rs17720428." (PMID 33667269, 2021). "Data mining of transcriptome profiles in endometrial tissues also indicated higher HOTAIR levels and functions in endometriosis patients at more advanced stages, suggesting potent roles in disease progression." (PMID 33667269, 2021). "We found that patients with aggressive endometriosis (at stage 4) expressed higher HOTAIR levels in their endometria as compared to normal controls without endometriosis (p = 0.0009)." (PMID 33667269, 2021). "Gene knockdown was also performed to confirm functional relevance of HOTAIR in cell proliferation and migration of endometriosis-related ovarian cells." (PMID 33667269, 2021). "Targeting HOTAIR is a potential strategy for treating endometriosis and suppressing further malignant transition." (PMID 33667269, 2021). "Data mining further revealed higher mRNA HOTAIR levels in the endometria of patients with severe endometriosis which consistently showed reduced HOXD10 and HOXA5 levels." (PMID 33667269, 2021). "Dominant and recessive effects of the selected SNPs in HOTAIR gene between Taiwanese endometriosis patients and controls." (PMID 33667269, 2021). "The present study aimed to investigate whether LncRNA HOTAIR regulates cell invasion and migration in endometriosis by regulating the miR-519b-3p/PRRG4 pathway." (PMID 36338672, 2022). "Our study therefore provided evidence to indicate a prominent role of HOTAIR in promoting endometriosis, which could be used as a potential target for clinical applications." (PMID 33667269, 2021).
endometriosis (continued). "HOTAIR is a well-known long non-coding RNA (lncRNA) involved in various cellular signaling, whereas its functional impacts on endometriosis development are still largely unknown." (PMID 33667269, 2021). "Higher levels of HOTAIR mRNA have been shown in endometrial patients with severe endometriosis." (PMID 34638893, 2021). "Our results support a potent role for elevated HOTAIR in endometriosis development." (PMID 33667269, 2021). "Research indicates a significant role for HOTAIR in promoting endometriosis." (PMID 34638893, 2021). "Although the pro-oncogenic roles of HOTAIR in cancer have been well addressed, it remains totally unknown for its roles in the development and progression of endometriosis." (PMID 33667269, 2021). "Since HOTAIR has been reported to be involved in cell proliferation and migration/invasion, we proposed that alterations in its RNA structure and function by genetic variations may contribute to endometriosis development." (PMID 33667269, 2021). "Moreover, endometriosis pathogenesis may revolve around a functional axis of HOTAIR/homeobox D10 and HOTAIR/homeobox A5." (PMID 34638965, 2021). "Thus, HOTAIR may mediate the degradation of miR-519b-3p in endometriosis." (PMID 36338672, 2022). "Our data confirm the molecular link between HOTAIR and those homeobox proteins, suggesting the involvement of HOXD10 and HOXA5 in endometriosis progression." (PMID 33667269, 2021). "Since oncogenic lncRNAs like HOTAIR can interact with many miRNAs as decoys or sponges to establish competing endogenous RNA (ceRNA) networks for malignant transformation, whether HOTAIR forms a complex with mir196a2 to promote endometriosis progression is worthy of further investigation." (PMID 33667269, 2021). "In addition, our data indicated that functional axes of HOTAIR/HOXD10 and HOTAIR/HOXA5 may play potent roles in regulating endometriosis progression." (PMID 33667269, 2021).
medulloblastoma (6 papers, 2021 to 2024). A malignant, invasive embryonal neoplasm arising from the cerebellum. "Other players implicated in the tumorigenic actions of HOTAIR in medulloblastoma pathogenesis include miR-1 and miR-206, both of which are its sponging targets, and have the capacity to modulate expression of zinc finger transcriptional repressor, Yin Yang 1 (YY1)." (PMID 38366205, 2024). "Correspondingly, repression of HOTAIR was observed to alter miR-1/miR-206-YY1 signaling in favor of repression of medulloblastoma cell proliferation, migration and epithelial to mesenchymal transition (EMT), and induction of apoptosis." (PMID 38366205, 2024). "Through miR-1/miR-206-YY1 pathway, HOTAIR suppression leads to increased apoptosis in medulloblastoma." (PMID 35111757, 2021). "The knockdown of lncRNA CRNDE induces apoptosis via promoting the activity of caspase-3 in medulloblastoma cells Cleaved-caspase-3, caspase-9, and Bax elevation, and bcl-2 reduction are the results of HOTAIR downregulation in medulloblastoma cells." (PMID 35111757, 2021). "In medulloblastoma cells, HOTAIR is able to negatively regulate miR-1 and miR-206 expression which can directly target YY1, a transcription factor described as a metastasis inducer." (PMID 34576322, 2021). "Medulloblastoma tissues are observed to have elevated levels of LncRNA HOTAIR which binds to miR-1 and miR-206 and inhibits them to upregulate YY1." (PMID 35111757, 2021). "Another molecular axis involving HOTAIR, miR-483-3p, and CDK4 is strongly associated with medulloblastoma progression." (PMID 33540611, 2021). "Two recent studies described the ability of HOTAIR to bind to different miRNAs during medulloblastoma progression." (PMID 33540611, 2021). "HOTAIR appeared overexpressed in ATRTs, medulloblastomas and JPAs, and downregulated in ependymomas." (PMID 34576322, 2021). "HOTAIR, NEAT1, linc-NeD125, HHIP-AS1, CRNDE, and TP73-AS1 are the oncogenic lncRNAs, and Nkx2-2as is a tumor-suppressive lncRNA that develop lncRNA-associated ceRNA networks in medulloblastoma." (PMID 39010056, 2024). "Overall, the current evidence indicates that HOTAIR, NEAT1, linc-NeD125, HHIP-AS1, CRNDE, and TP73-AS1 are oncogenic lncRNAs and Nkx2-2as is a tumor-suppressive lncRNA that forms lncRNA-associated ceRNAs in medulloblastoma." (PMID 39010056, 2024). "HOTAIR upregulation has also been detected in medulloblastoma tissues and cell lines." (PMID 34576322, 2021). "Finally, HOTAIR knockdown suppressed medulloblastoma cell proliferation, tumor growth, migration and invasion, and promoted cell apoptosis via the modulation of the miR-1/miR-206-YY1 axis, as well as EMT." (PMID 34576322, 2021). "HOTAIR, NEAT1, linc-NeD125, HHIP-AS1, CRNDE, and TP73-AS1 are the identified oncogenic lncRNA in medulloblastoma, and Nkx2-2as is a tumor-suppressive lncRNA in medulloblastoma." (PMID 39010056, 2024). "HOTAIR, downregulating miR-1 and miR-206, increases YY1 expression, promoting tumor growth, migration, invasion, and EMT of medulloblastoma cells." (PMID 33540611, 2021). "Indeed, elevated levels of HOTAIR and YY1 have been observed in tissues from clinical cases of human medulloblastoma, and in Daoy, D283 Med and D341 cell lines." (PMID 38366205, 2024). "HOTAIR knockdown improves apoptosis rate, decreases the cell viability, clonogenicity, migration, and invasion, and reduces tumor volume in animal models; this oncogenic effect is medicated via the HOTAIR/miR-1-3p and miR-206/ YY1 axes in medulloblastoma." (PMID 39010056, 2024).
myocardial infarction (6 papers, 2019 to 2024). Gross necrosis of the myocardium, as a result of interruption of the blood supply to the area, as in coronary thrombosis. "HOTAIR has been identified as a negative regulator of myocardial infarction in murine models, operating through the modulation of miR-519d-3p." (PMID 39172906, 2024). "Another study reported that HOTAIR was significantly downregulated in the early phase of acute myocardial infarction." (PMID 34064346, 2021). "In recent research, HOTAIR was a crucial mediator in an acute myocardial infarction event." (PMID 36361470, 2022). "HOTAIR inactivates miR-1, which is involved in acute myocardial infarction (AMI) and sponging miR-613 to regulate Connexin 43 in atrial fibrillation, suggesting a protective role for HOTAIR in this disease." (PMID 34064346, 2021). "This indicates that HOTAIR is a promising candidate as a clinical biomarker for non-invasive diagnosis and potential therapeutic target for myocardial infarction." (PMID 31379598, 2019).
neuroblastoma (6 papers, 2017 to 2023). Neuroblastoma (NB) is the most common solid, extracranial childhood tumor. "This study sheds light on the association of important HOTAIR gene polymorphisms with neuroblastoma susceptibility." (PMID 35592755, 2022). "The expression of HOTAIR and LRRK2 were detected in the PD mice and in human neuroblastoma cell lines SH-SY5Y pretreated with MPP+." (PMID 28445933, 2017).
osteoporosis (6 papers, 2020 to 2024). A condition of reduced bone mass, with decreased cortical thickness and a decrease in the number and size of the trabeculae of cancellous bone (but normal chemical composition), resulting in increased fracture incidence. "The studies reviewed here suggest that HOTAIR plays a role in the development of various diseases, including cancer, osteonecrosis, and osteoporosis." (PMID 39156986, 2024). "By intersecting the target miRNAs of HOTAIR, the target miRNAs of NNMT, and the DE-miRNAs of GSE91033, we identified miR-378g as a potential miRNA that linked HOTAIR and NNMT in osteoporosis." (PMID 34895051, 2021). "HOTAIR exacerbates bone marrow mesenchymal stem cell-mediated osteoporosis through sponging miR-378g." (PMID 34895051, 2021). "In conclusion, our findings demonstrated a novel role of oestrogen in the development of osteoporosis by regulating the expression of HOTAIR." (PMID 33733597, 2021). "Finally, a higher expression level of TIMP1 protein also increased the viability and reduced the apoptosis of osteoblasts, confirming the role of HOTAIR in the pathogenesis of osteoporosis among post‐menopausal females." (PMID 33733597, 2021). "Finally, we confirmed that oestrogen could at least partially affect the progress of osteoporosis by controlling the apoptosis of osteoblasts and by up‐regulating the expression of HOTAIR, an lncRNA playing a protective role against osteoporosis." (PMID 33733597, 2021). "Therefore, it can be concluded that oestrogen deficiency could induce the apoptosis of osteoblasts and lead to osteoporosis in post‐menopausal females via modulation of the HOTAIR/miR‐138/TIMP1 signalling axis." (PMID 33733597, 2021). "Several lncRNAs, including Malat1, H19, HOTAIR, MEG3 and DANCR, were largely involved in the osteoporosis." (PMID 36983039, 2023). "However, the ceRNA mechanism involving HOTAIR has not been reported for osteoporosis." (PMID 34895051, 2021).
retinoblastoma (6 papers, 2018 to 2024). A malignant tumor that originates in the nuclear layer of the retina. "Consequently, up‐regulated HOTAIR and down‐regulated miR‐613 expressions displayed associations with poor survival status of retinoblastoma patients (P < 0.05)." (PMID 30030888, 2018). "In the study examining HOTAIR in retinoblastoma, HOTAIR was shown to be engaged in a reciprocal regulatory loop with miR-613 and promoted cell proliferation and activation of the EMT, potentially through upregulation of N-cadherin, vimentin, and α‐SMA." (PMID 31616462, 2019). "In addition, miR‐613 expression followed the trend opposite to HOTAIR, regarding its expression within retinoblastoma tissues (P < 0.05)." (PMID 30030888, 2018). "Since lncRNAs could modulate neoplastic development by modulating downstream miRNAs and genes, this study was carried out to figure out the synthetic contribution of HOTAIR, miR‐613 and c‐met to viability, apoptosis and proliferation of retinoblastoma cells." (PMID 30030888, 2018). "In conclusion, the role of lncRNA HOTAIR/miR‐613/c‐met signalling axis in modulating retinoblastoma cells’ viability, apoptosis and expressions of EMT‐specific proteins might provide evidences for developing appropriate diagnostic and treatment strategies for retinoblastoma." (PMID 30030888, 2018). "Conclusively, our study results initially manifested that highly expressed HOTAIR could promote development and aggravation of retinoblastoma by miR‐613/c‐met axis, providing strong evidences for developing potential diagnostic biomarkers and treatment targets for retinoblastoma." (PMID 30030888, 2018). "LncRNAs PVT1, AFAP10AS1, HOTAIR, BANCR, H19, DANCR and LINC00202 were up-regulated in retinoblastoma tissues while MT1JP and BDNF-AS were down-regulated." (PMID 32514246, 2020). "Our RT‐PCR results also verified that MEG3, HOTAIR, CCAT1 expressions within retinoblastoma tissues were far beyond those within para‐carcinoma tissues (P < 0.01)." (PMID 30030888, 2018). "The results of microarray analysis showed that lncRNAs HOTAIR, CCAT1, DNM3OS, HIF1A‐AS1, MEG3 and 7SK expressions were up‐regulated, and lncRNAs PCAT1, MIR31HG, BCAR4, RRP1B and H19 were down‐regulated within retinoblastoma tissues." (PMID 30030888, 2018). "Meanwhile, there was a negative correlation between HOTAIR and miR‐613 expressions within retinoblastoma tissues (P < 0.05)." (PMID 30030888, 2018). "Moreover, transfections of pcDNA3.1‐HOTAIR, si‐HOTAIR, miR‐613 mimic, miR‐613 inhibitor, pcDNA3.1/c‐met were performed to evaluate the influence of HOTAIR, miR‐613 and c‐met on viability, apoptosis and epithelial‐mesenchymal transition (EMT) of retinoblastoma cells." (PMID 30030888, 2018).
sarcoma (6 papers, 2017 to 2023). A usually aggressive malignant neoplasm of the soft tissue or bone. "Overexpression of HOTAIR was involved in drug resistance in primary sarcoma and decreased levels of HOTAIR were associated with good chemoresponse, suggesting that clinical application of HOTAIR may be a potential predictor of treatment efficacy." (PMID 28978183, 2017). "Across all tissues and cell types, lncHUB2 reports suggest that HOTAIR has the highest relative expression in synovial tissue and sarcoma." (PMID 36869839, 2023). "High level expression of HOTAIR in the primary sarcoma was also significantly related to metastasis." (PMID 29113307, 2017). "Finally, high HOTAIR levels in primary sarcoma correlated with a high metastasis probability." (PMID 32117729, 2020). "Analysis of available data generated by siRNA knock-down of HOTAIR in an HCC cell line HepG2, and human sarcoma cell lines ES2, A673 and SK-ES supported our in-vitro HOTAIR knock-down data in HuH-7 cells." (PMID 32650779, 2020).
brain cancer (5 papers, 2021 to 2025). A primary or metastatic malignant neoplasm affecting the brain. "This comprehensive review aims to accumulate and summarize the evidences of the involvement of HOTAIR in multiple pathogenic mechanisms central to the progression of brains cancers and other CNS disorders." (PMID 38682637, 2024). "SNPs of HOTAIR have been linked to multiple neuropathologies, including MS, neuropsychiatric conditions and brain cancers." (PMID 38682637, 2024). "In addition, the expression of HOTAIR was found to be strongly associated with high-grade brain cancers, and Pearson’s correlation analysis revealed a moderate association between serum and tumor HOTAIR levels." (PMID 34722277, 2021). "We also direct the attention of the readers to relevance of HOTAIR as a particularly interesting marker for disease diagnosis/prognosis, as well as a bio-target for the design of therapeutic strategies against CNS pathologies, including brain cancers." (PMID 38682637, 2024). "In fact, HOTAIR represents one of the most prominent and extensively studied lncRNAs which are often found to be hyperactivated in multiple human tumor types, including breast, lung, gastric, colorectal, cervical, and brain cancers." (PMID 38366205, 2024). "Some of the most representative lncRNAs, such as HOTAIR, MALAT1, and MEG3, have been consistently validated over the years, where their role in malignant brain tumors appears evident." (PMID 41149459, 2025).
breast invasive carcinoma (5 papers, 2017 to 2022). "Based on the subclasses, the UALCAN results showed that HOTAIR was overexpressed in breast invasive carcinoma compared with normal tissues." (PMID 36233075, 2022). "Similar pathways were identified as activated in primary invasive breast carcinomas with HOTAIR over-expression." (PMID 34869037, 2021). "HOTAIR belongs to the first lncRNAs described as aberrantly expressed in invasive breast carcinomas." (PMID 34869037, 2021). "In this study, we analyzed the HOTAIR expression in breast invasive carcinoma tissues derived from TCGA (The Cancer Genome Atlas) which applies RNA sequencing of large cohorts." (PMID 29209357, 2017). "The TCGA invasive breast carcinoma RNA‐Seq data were surveyed for expression of HOTAIR isoforms using RSEM." (PMID 28846832, 2017). "While MET expression was significantly suppressed in primary tumor tissues in breast invasive carcinoma (BRCA) and upregulated in kidney chromophobe (KIHC), HOTAIR expression was significantly higher and lower, respectively." (PMID 32650779, 2020).
laryngeal carcinoma (5 papers, 2018 to 2024). Carcinoma that arises from the laryngeal epithelium. "Several recent studies have reported that multiple lncRNAs are involved in the progression of head and neck cancer; for example, H19, NEAT1, and HOTAIR are overexpressed in laryngeal cancer." (PMID 32039035, 2019). "Similarly, in 2014, Wang et al40 discovered that serum exosomal miR‐21 and HOTAIR in laryngeal carcinoma patients can serve as prognostic biomarkers." (PMID 29971915, 2018). "Exosomal HOTAIR was shown to induce macrophage M2 polarization through activation of the PI3K/AKT signaling pathway, thereby promoting EMT and metastasis of laryngeal carcinoma cells." (PMID 38339237, 2024).